MEF2D (myocyte enhancer factor 2D)
Description:
Transcriptional activator which binds specifically to the MEF2 element, 5'-YTA[AT](4)TAR-3', found in numerous muscle-specific, growth factor- and stress-induced genes. Mediates cellular functions not only in skeletal and cardiac muscle development, but also in neuronal differentiation and survival. Plays diverse roles in the control of cell growth, survival and apoptosis via p38 MAPK signaling in muscle-specific and/or growth factor-related transcription. Plays a critical role in the regulation of neuronal apoptosis (By similarity).
Tractability: PROTAC: UniProt records ubiquitination sites on it; ubiquitination databases record sites on it; its protein half-life has been measured.
Gene: Protein-coding gene on chromosome 1 (156,463,727 to 156,501,266, reverse strand). Ensembl gene ENSG00000116604.
Subcellular location: Nucleus
Subcellular location (Human Protein Atlas): Nucleoplasm; Vesicles
Pathways (Reactome):
Cellular responses to stimuli: Heme signaling
Circadian clock: Expression of BMAL (ARNTL), CLOCK, and NPAS2
Developmental Biology: Myogenesis
Organelle biogenesis and maintenance: Transcriptional activation of mitochondrial biogenesis
Signal Transduction: NGF-stimulated transcription
Gene Ontology:
Molecular function: DNA-binding transcription factor activity, RNA polymerase II-specific; DNA-binding transcription factor binding; histone deacetylase binding; protein binding; RNA polymerase II transcription regulatory region sequence-specific DNA binding; RNA polymerase II-specific DNA-binding transcription factor binding; sequence-specific double-stranded DNA binding; DNA-binding transcription factor activity; RNA polymerase II cis-regulatory region sequence-specific DNA binding; DNA binding; protein dimerization activity
Biological process: adult heart development; positive regulation of transcription by RNA polymerase II; positive regulation of vascular associated smooth muscle cell proliferation; cell differentiation; muscle organ development; animal organ development
Cellular component: nucleoplasm; nucleus; chromatin
Genetic constraint (gnomAD): Loss-of-function variants: 10 observed, 59.45 expected, observed/expected ratio (o/e) 0.17, 90% interval 0.1 to 0.28. The upper end of that interval is the gene's LOEUF score, 0.28, which puts it in group 1 of 6, group 1 being the genes least tolerant of losing a copy. Missense variants: 508 observed, 708.55 expected, observed/expected ratio (o/e) 0.72, 90% interval 0.67 to 0.77. Synonymous variants: 305 observed, 297.89 expected, observed/expected ratio (o/e) 1.02, 90% interval 0.93 to 1.13.
Homologues: Orthologues: chimpanzee MEF2D (99% identical), macaque MEF2D (99% identical), guinea pig MEF2D (96% identical), rabbit MEF2D (96% identical), pig MEF2D (96% identical), rat Mef2d (96% identical), dog MEF2D (95% identical), mouse Mef2d (87% identical), tropical clawed frog mef2d (74% identical), zebrafish mef2d (68% identical). Paralogues in human: MEF2A (56% identical), MEF2C (51% identical), MEF2B (30% identical), SRF (17% identical).
Diseases named in the same sentence as MEF2D in open-access papers:
MEF2D is named in the same sentence as 92 diseases in open-access papers, as found by Europe PMC text mining. Sharing a sentence is not in itself a finding about the gene and the disease. The quoted sentences say what the papers report.
hepatocellular carcinoma (21 papers, 2015 to 2025). A malignant tumor that arises from hepatocytes. "Silencing of MEF2D triggers G2‐M arrest in a way associated with direct down‐regulation of genes related to cell cycle progress in hepatocellular carcinoma." (PMID 34109727, 2021). "It has been implicated that MEF2D is involved in different types of malignancies, including acute lymphoblastic leukemia, hepatocellular carcinoma and osteosarcoma." (PMID 28340574, 2017). "Notably, in patients diagnosed with osteosarcoma, hepatocellular carcinoma or colorectal cancer, poorer prognosis is associated with greater MEF2D expression." (PMID 29029385, 2017). "MEF2A and -C mRNA and protein abundance tended to be greater in hepatocellular carcinoma (HCC) cells than normal liver cells and MEF2D expression in HCC patient samples was associated with poor prognosis." (PMID 26506234, 2016). "Correspondingly, high levels of MEF2D expression have been shown to be correlated with a poor patient prognosis, and MEF2D suppression has been shown to decrease the proliferation of hepatocellular carcinoma, osteosarcoma, and glioma." (PMID 38791246, 2024). "A previous study reported that SIRT7 formed a complex with MEF2D that suppressed PD-L1 expression in hepatocellular carcinoma, which was different from our present study that SIRT7 facilitated PD-L1 expression under ER stress in melanoma." (PMID 36918544, 2023). "KDM1A reinforces the immunosuppression in hepatocellular carcinoma through demethylating MEF2D and activating PD-L139." (PMID 36357457, 2022). "Subsequent evidence showed that MEF2D exerted significant roles in the progression of hepatocellular carcinoma, colorectal cancer, lung cancer, and osteosarcoma." (PMID 35069734, 2022). "Elevated MEF2D expression is detected in hepatocellular carcinoma clinical specimens, especially in those with poor prognosis." (PMID 34109727, 2021). "Accordingly, one of its members, MEF2D, has been related to lung cancer, hepatocellular carcinoma, and glioma, with its expression regulated by miR‐1244, miR‐122, and miR‐18a, respectively." (PMID 31930767, 2020). "MEF-2D is also implicated in angiogenesis and EMT via TGF-β in an autoregulatory mechanism in hepatocellular carcinoma (HCC)." (PMID 31105874, 2019). "Among the miR-361 target genes identified in this study, MEF2D is involved in tumor promotion in pancreatic cancer, hepatocellular carcinoma, osteosarcoma, lung cancer, gastric cancer, colorectal cancer, and osteosarcoma." (PMID 31287002, 2019). "MEF2D has been reported to serve as oncogene in B cell acute lymphoblastic leukemia and hepatocellular carcinoma through promotion of colony formation and proliferation, inhibition of apoptosis, epithelial-mesenchymal transition and invasiveness." (PMID 28340574, 2017). "The expression of MEF2D is up-regulated in hepatocellular carcinoma (HCC) and this increase can accelerate cell proliferation in HCC." (PMID 29340119, 2017). "Similarly, miR-122 and miR-1244 negatively regulate MEF2D expression in hepatocellular carcinoma and lung cancer cells, respectively." (PMID 29340119, 2017). "In hepatocellular carcinoma (HCC), the elevated programmed cell death ligand 1 (PD-L1) expression downstream of myocyte enhancer factor 2 (MEF2D) orchestrates immune escape." (PMID 37676263, 2024). "Notably, an increasing number of studies have detected the overexpression of MEF2D in non-small cell lung cancer (NSCLC), colorectal cancer, hepatocellular carcinoma, osteosarcoma, and glioma." (PMID 38791246, 2024). "In hepatocellular carcinoma (HCC), SIRT7 directly deacetylates the transcription factor myocyte enhancer factor 2D (MEF2D), thereby reducing its transcriptional activity and suppressing PD-L1 expression." (PMID 41471367, 2025).
lung carcinoma (19 papers, 2014 to 2025). "MEF2D might be a potential biomarker during chronic inflammation-lung cancer transition, predicting the risk of lung cancer among patients with chronic respiratory diseases." (PMID 28340574, 2017). "MEF2D could be a potential biomarker predicting risk of lung cancer among patient with chronic respiratory diseases." (PMID 28340574, 2017). "We now report that as with Mef2d, the deletion of Mef2c in Tregs switches off the expression of Il10 and Icos and leads to enhanced antitumor immunity in syngeneic models of lung cancer." (PMID 34290714, 2021). "MEF2D is also observed abundant in lung cancer tissues and cell lines comparing with the matched normal tissues and cell lines." (PMID 34109727, 2021). "The aberrant expression of miR-30a in lung cancer stimulated the expression of myocyte enhancer factor 2D (MEF2D) protein." (PMID 33546236, 2021). "For example, the knockdown of MEF2D leads to impaired proliferation and the migration of lung cancer cells." (PMID 33066509, 2020). "The study predicts that miR-30a targets the 3′UTR of MEF-2D mRNA and promotes apoptosis in lung cancer cells." (PMID 31105874, 2019). "For instances, oleanolic acid is a new type of anti-tumor drugs that suppresses proliferation of lung cancer cells via inhibition of MEF2D expression." (PMID 29340119, 2017). "Much more remains to be learned about the regulatory mechanism of MEF2D to communicate between chronic inflammation and lung cancer." (PMID 28340574, 2017). "As far as we know, this is the first study focused on MEF2D as a “communicator” between chronic inflammation and lung cancer." (PMID 28340574, 2017). "Interestingly, this study reports that Mef2d plays a crucial role as a key mediator linking LPS-stimulated inflammation and lung cancer progression by influencing the cancer microenvironment and cellular behavior." (PMID 40076622, 2025). "Inflammatory conditions increase MEF2D expression in lung cancer cells, which might contribute to cancer development by influencing cancer microenvironment and cell bio‐behaviours." (PMID 34109727, 2021). "Knocking down of MEF2D by miRNA interference suppresses the growth of lung carcinoma." (PMID 34109727, 2021). "In addition, expression of miR-30a inhibitor the growth of lung cancer cells by targeting MEF2D (Luan, Wang & Liu, 2018)." (PMID 34178448, 2021). "Furthermore, it was noticed that the treatment of lung cancer cells with oleanolic acid upregulates miR-122 and downregulates two target mRNAs of this miRNA, namely MEF2D and cyclin G1, resulting in the suppression of cell proliferation." (PMID 33066509, 2020). "MEF-2D is involved in cancer of the colorectal tissue, breast, prostate, lung, liver, and thyroid.Implicated in melanoma, and pathobiology of B-cell acute lymphoblastic leukemia (B-ALL).Also, Parkinson's disease, cardiac myxoma, and lung cancer." (PMID 31105874, 2019). "Studies in vitro have shown an anti-cancer function of miR-218, and the down-expression of miR-218 increases myocyte enhancer factor 2D (MEF2D) levels by promoting lung cancer growth, and by inhibiting NSCLC proliferation and metastasis via by downregulating CDCP1." (PMID 28915579, 2017). "Up-regulation of MEF2D during inflammatory condition might favor lung cancer cell differentiation, proliferation, or movement." (PMID 28340574, 2017). "MEF2D might contribute to the development of lung cancer through influencing cancer microenvironment and cell bio-behaviors during inflammatory conditions." (PMID 28340574, 2017). "Recently, MEF2D has been reported to promote the growth of lung cancer." (PMID 28340574, 2017). "MEF2D might be a potential biomarker for patients with chronic respiratory diseases, such as COPD, who are at risk of developing lung cancer." (PMID 28340574, 2017). "Inflammatory conditions led to increased MEF2D expression, which might further contribute to the development of lung cancer through influencing cancer microenvironment and cell bio-behaviors." (PMID 28340574, 2017).
lung carcinoma (continued). "The results prompted us to further speculate whether MEF2D might act as a communicator between inflammation and lung cancer." (PMID 28340574, 2017). "Moreover, a molecular regulatory loop whereby MEF2D regulates miR‐1244 was observed in lung cancer." (PMID 31930767, 2020). "Furthermore, MEF2D regulate miR-1244 by directly binding to its promoter and this molecular regulatory loop could be a target for lung carcinoma treatment." (PMID 29340119, 2017). "In addition, overexpression of CCNG1 (cyclin G1) and MEF2D (myocyte enhancer factor 2D), two targets of miR-122 also abolished the antitumor effect in lung cancer, which indicates that oleanolic acid may inhibit lung cancer growth through miR-122/CCNG1/MEF2D pathway." (PMID 28052018, 2017). "Like lung cancer, in these Rhabdoid studies, we found that HDAC3, HDAC9, GATA3 and MEF2D regulate BRM." (PMID 24913006, 2014). "In both lung cancer and Rhabdoid cell lines, we have found that HDAC9 and MEF2D bind to the BRM promoter." (PMID 24913006, 2014). "Similar to lung cancer cell lines, we found that HDAC3, HDAC9, MEF2D and GATA3 controlled BRM silencing and that HDAC9 was overexpressed in Rhabdoid cancer cell lines." (PMID 24913006, 2014). "Similar to our published studies with lung cancer, we found that BRM was also regulated by HDAC3, HDAC9, GATA3, and MEF2D in Rhabdoid tumors." (PMID 24913006, 2014). "Similar to lung cancer cell lines, GATA3 and MEF2D regulate both HDAC9 and BRM." (PMID 24913006, 2014). "Also, the lack of its expression promotes the growth of lung cancer cells by targeting MEF2D." (PMID 34750486, 2021).
leukemia (13 papers, 2014 to 2025). A malignant (clonal) hematologic disorder, involving hematopoietic stem cells and characterized by the presence of primitive or atypical myeloid or lymphoid cells in the bone marrow and the blood. "It has been reported that MEF2D rearrangements can enhance its transcriptional activity and lymphoid transformation, thus contributing to the development of a high-risk leukemia." (PMID 38907739, 2024). "Interestingly, this pattern resembles a previously recognized leukemia-associated TF circuitry that is active in the MEF2D-fusion subtype of ALL." (PMID 38822412, 2024). "Thus, MEF2D-rearranged ALL represents a distinct form of high-risk leukaemia, for which new therapeutic approaches should be considered." (PMID 27824051, 2016). "By employing a large-scale drug screening, we discovered that inhibitors of PI3K pathway, MAPK pathway, BCL2 family, and HDAC were found to significantly suppressed in vitro proliferation of leukemia cells harboring the MEF2D fusion gene." (PMID 40695793, 2025). "While MEF2C is a well-established transcriptional dependency of KMT2A-rearranged AML, the role of MEF2D in leukemia has remained relatively unexplored." (PMID 35301220, 2022). "Firstly, it was reported in the experimental study of leukemia that MEF2D promoted the malignant transformation of normal cells." (PMID 35069734, 2022). "The observation that KMT2A-rearranged leukemias depend on the IRF8/MEF2D axis for expression of common leukemia oncogenes raises the question of how expression of these oncogenes is maintained in non-KMT2Ar contexts." (PMID 35301220, 2022). "While colony-forming assays are crude models of normal hematopoiesis, our results are consistent with MEF2D being a specific transcriptional addiction of KMT2Ar leukemia." (PMID 35301220, 2022). "Further studies will be needed to elucidate the mechanistic basis of the IRF8/MEF2D module activation and the selective, context-specific dependence on these TFs for the expression of common oncogenes in KMT2Ar leukemia." (PMID 35301220, 2022). "The leukemias with the next highest relative ELP signals were PAX5 and MEF2D-mutated B-ALL, although the ELP signals there were accompanied by stronger signals from later B-cell stages." (PMID 35288693, 2022). "MEF2D-rearranged leukemias display a distinct gene expression signature, which showed substantial overlap and agreement with differentially abundant proteins in the MEF2D-HNRNPUL1 cell lines." (PMID 35354797, 2022). "Because IRF8 and MEF2D were the most strongly selective transcriptional dependencies of KMT2Ar leukemia and most strongly overexpressed core TFs in primary KMT2Ar AML samples, we focused attention on these two TFs." (PMID 35301220, 2022). "Myocyte enhancer factor 2D (MEF2D) is a transcription factor that is upregulated in various cancers, such as osteosarcoma, leukemia and GC." (PMID 34425750, 2021). "The distinct gene expression profile, tumour cell immunophenotype, older age of onset and poor outcome of MEF2D-rearranged ALL cases together suggest that MEF2D-rearranged ALL represents a biologically distinct form of leukaemia." (PMID 27824051, 2016). "The poor outcome of MEF2D-rearranged ALL suggests that new therapeutic approaches directed against deregulated cellular pathways observed in this form of leukaemia are warranted." (PMID 27824051, 2016). "The transcription factor MEF2D, a recently identified oncogene in leukemia and liver cancer, appeared to be more abundant in ESCC cells than in HET-1A cells." (PMID 24797725, 2014). "Importantly, rather than regulating a KMT2Ar-specific transcriptional program, the IRF8/MEF2D module enforces expression of ubiquitous leukemia oncogenes." (PMID 35301220, 2022). "Thus, MEF2C may activate expression of HOXA9 in non-KMT2Ar leukemias, while the role of MEF2D is restricted to KMT2Ar AML." (PMID 35301220, 2022). "Thus, further study of this therapeutic strategy in MEF2D-HNRNPUL1 fusion leukemias is merited." (PMID 35354797, 2022).
leukemia (continued). "We independently confirmed the selective dependency of KMT2Ar leukemia on IRF8 and MEF2D by measuring cell viability after CRISPR–Cas9 TF knockout in a panel of six cell lines." (PMID 35301220, 2022). "In contrast, deregulated MEF2D activity, with activation of HDAC9 and resulting inhibition of MEF2C were characteristic of this form of leukaemia." (PMID 27824051, 2016). "Further studies are required to dissect the relative role of MEF2D and partner gene involvement in leukaemogenesis, but our existing data suggest the potential for HDAC inhibition in this form of leukaemia." (PMID 27824051, 2016). "Of note, MEF2D fusion (+) leukemia blasts did not develop into immature B cells and therefore had no expression of the whole set of BCR signaling molecules." (PMID 40695793, 2025). "While our data do not reveal a fusion protein-driven mechanism of IRF8/MEF2D axis activation in KMT2A-rearranged leukemia, we found that it correlates with the degree of myeloid differentiation." (PMID 35301220, 2022). "Myocyte enhancer factor 2D (MEF2D)-rearranged ALL arise in around 4% of pediatric ALL and may be considered as a biologically distinct form of leukemia." (PMID 33255367, 2020). "Unlike IRF8, which plays an essential role in myeloid development, MEF2D has no assigned role in normal hematopoiesis, prompting us to hypothesize that it represents a leukemia-specific transcriptional addiction." (PMID 35301220, 2022). "Additionally, myocyte enhancer factor-2D (MEF2D) rearrangements, such as the MEF2D-HNRNPU1 (MH) fusion, aberrantly activate MEF2D’s transcriptional activity, disrupt the expression of genes related to B-cell development, and promote the malignant proliferation of leukemia cells." (PMID 41155287, 2025). "This concept is further illustrated by the KMT2A-like leukemias, which express high levels of IRF8 and MEF2D despite the absence of a KMT2A translocation." (PMID 35301220, 2022). "Indeed, several of the IRF8/MEF2D direct target genes, such as MYC, HOXA9, and ZEB2, are highly expressed and essential in non-KMT2Ar leukemias and normal hematopoietic progenitors that do not express high levels of IRF8/MEF2D." (PMID 35301220, 2022).